AURKA (aurora kinase A)
Diseases named in the same sentence as AURKA in open-access papers (continued):
Sharing a sentence is not in itself a finding about the gene and the disease.
cancer (continued). "AURKA also exhibited significant correlations with ESTIMATE and immune scores, TMB, MSI, CNV, and the TIDE score in most cancers, including ESCA." (PMID 37965456, 2023). "Two of the three Aurora kinase family members, Aurora-A (AURKA) and B (AURKB), are essential to regulate cell division and in cancer and work as oncogenes for solid malignancies." (PMID 36752780, 2023). "More specifically, aurora kinase A (AURKA) belongs to the serine/threonine kinases, the TGCA has shown are more highly expressed in cancer cells than in normal control cells." (PMID 36752780, 2023). "Further mechanistic experiments will be undertaken to elucidate the AURKA pathways governing the progression of EAC and other cancers." (PMID 37965456, 2023). "AURKA and AURKB have been extensively studied in the context of cancer as their genes are frequently overexpressed/amplified in solid tumors and hematological malignancies." (PMID 35054947, 2022). "Targeting AURKA can significantly reverse prosurvival UPR signaling mechanisms and decrease cancer cell survival, providing a promising approach for the treatment of EAC patients." (PMID 35326553, 2022). "The findings revealed that AURKA was highly expressed in ACC and most cancers and that its expression level increased as ACC progressed." (PMID 36685952, 2022). "AURKA overexpression constitutively activates CDK1 and abolishes the G2/M DNA damage checkpoint in cancer cells." (PMID 35699421, 2022). "In this study, we report, for the first time, that AURKA hijacks prosurvival UPR in EAC, promoting the survival of cancer cells under reflux-mediated stress conditions." (PMID 35326553, 2022). "The AURKA-selective inhibitor Alisertib has passed phase III, but none of the kinase inhibitors have yet been approved as an anti-cancer drug." (PMID 35054947, 2022). "AURKA and AURKB have been found to function as oncogenes and promote tumorigenesis in various cancers, including solid tumors and hematologic malignancies." (PMID 36291769, 2022). "This 12-gene assay is used to obtain a score based on the expression of 7 cancer-related genes (Ki67, AURKA/STK15, BIRC5/survivin, CCNB1, MYBL2, PGR, and GSTM1) and 5 normalizing reference genes (ACTB, GAPDH, RPLPO, GUS, and TFRC)." (PMID 36096802, 2022). "In summary, our results demonstrated that IDOAMP inhibited Aurora kinase A, promoting the RIPK1/RIPK3/MLKL necrosome activation to antiprostate cancer." (PMID 35965682, 2022). "Although AURKA and DOCK2 have been extensively reported to be closely related to cell proliferation and migration of cancer cells, the function of these two molecules in WJ-MSCs has not yet been studied extensively." (PMID 35450345, 2022). "Only AURKA, BIRC5, and PLAUR were served as the chemotherapy targets for cancer treatment currently." (PMID 33892811, 2021). "AURKA and AURKB have been found to function as oncogenes to promote tumorigenesis in multiple types of cancer including solid tumors and hematological malignancies." (PMID 33451333, 2021).
cancer (continued). "The AURKA overexpression was observed in many tumors, and AURKA promoted the oncogenic effects of c-Myc, which is frequently amplified and overexpressed in HCC and many other cancers." (PMID 34337035, 2021). "AURKA inhibitors, including MK5108, alisertib, and LY3295668, were found to induce selective toxicity toward RB1-mutant cancer cells by inducing apoptosis." (PMID 34050264, 2021). "The GDSC data set had a total of 47 unique drugs with ten targets, including EGFR, IGF1R, HDAC1, PARP2, AURKA, and BRAF, as well as their sensitivities across 224 cancer cell lines." (PMID 33795761, 2021). "Inhibition of AURKA or AURKB triggers transient mitotic arrest, polyploidization, and apoptosis of MYC expressing cancer, phenotypes reminiscent of those observed here for diMF." (PMID 33760847, 2021). "Among 12 genes reported in the literature as SL with RB1 6 genes (PPWD1, SKP2, AURKA, AURKB, E2F1, and E2F3) scored as SL RB1 partners in human cancer patients." (PMID 33591981, 2021). "In the present study, VEGFA, RRM2, H2AFX, CHEK1, CEP55, CDCA8 and AURKA were significantly upregulated; however, VCL, TPM2 and TPM1 were significantly downregulated in cancer samples of BC." (PMID 34112125, 2021). "Conversely, dual pharmacologic targeting of TGF-β and AURKA pathways efficiently reverses chemoresistance and impairs tumor progression through SNAI1 down-regulation, inhibition of cancer cell plasticity, and selective targeting of ALDH1high cells." (PMID 33674749, 2021). "Even though, AURKA has attracted researchers’ attentions and has been a more popular target than AURKB for cancer therapy with nearly fifty clinical trials using specific AKIs." (PMID 33451333, 2021). "To prove the validity of these in silico evaluations, we validate three novel target mRNAs by demonstrating that IGF2BP1 promotes the expression of AURKA, HDLBP, and YWHAZ in cancer cells by impairing decay of the respective mRNAs." (PMID 33829040, 2021). "AURKA genetic targeting impaired MPS growth, demonstrating the critical function of the AURKA signaling pathway in promoting cancer cells' self-renewal capacity." (PMID 33674749, 2021). "Two other AURKA inhibitors, MLN8237 and ENMD-2076, also enhance radiation sensitivity in cancer cells." (PMID 33451333, 2021). "Within this timeframe, many natural compounds have been developed to inhibit cancer growth by targeting kinases, such as AKT, AURKA, and TOPK." (PMID 34066486, 2021). "AURKA inhibitors and CDK inhibitors both have shown promise in the treatment of various types of cancer, including KRAS-mutant cancers." (PMID 34607583, 2021). "The KEGG pathway and Gene set enrichment analysis (GSEA) enrichment analysis results showed that AURKA and FAM83A are hub genes of cancer-related pathways." (PMID 33613763, 2021). "In summary, analysis of CALU co-expressed genes network as one the key regulators in tumor metastasis introduced a gene panel that consists of CALU, AURKA, and MCM2 with high discriminative accuracy between healthy and cancer (colon and lung) populations." (PMID 32469983, 2020).
cancer (continued). "Diagnostic accuracy estimation of differentially expressed genes showed that a gene panel consisted of CALU, AURKA, and MCM2 was able to successfully distinguish cancer tumors from healthy samples." (PMID 32469983, 2020). "Several downstream targets of AURKA have been identified including BRCA1, N-myc, GSK3β, LIMK2, TWIST1 and ALDH1A1 in various cancers." (PMID 33158056, 2020). "AURKA and AURKB also consistently scored high across every cancer cohort, as did other cell-cycle- and mitoses-related kinases (BUB1B, BUB1, CDK1)." (PMID 33205077, 2020). "AURKA can induce the metastasis of irradiated residuary HCC while promoting an epithelial-mesenchymal transition and cancer stem cell properties." (PMID 33505422, 2020). "Overexpression of AURKA and AURKB has been noted in many human cancers, where these proteins exhibit oncogenic properties." (PMID 33054831, 2020). "The deletion of UBE2C notably reduced the level of phosphorylated aurora kinase A via Wnt/β–catenin and PI3K/Akt and results in inhibition of the cancer growth and metastasis." (PMID 32703154, 2020). "In various types of cancers, numerous studies have now documented a link between EIF4A3, SMC3, ESPL1, CDC25B, CCNA2, or AURKA and their response to therapy." (PMID 32454908, 2020). "Western blot analysis of CALU, AURKA, and MCM2 proteins showed that the level of all of these candidate biomarkers was statistically increased through normal–carcinoma transition in both types of cancers." (PMID 32469983, 2020). "AURKA has been shown to be a downstream target of MAPK1, which is a major force in cellular proliferation in several cancer cells." (PMID 30679932, 2019). "The role of AURKA, PLK1 and FOXM1 in cancer pathogenesis and progression arises from their interaction with β-catenin, which is a central signal for normal and CML stem cells." (PMID 31122263, 2019). "Aurora A kinase (AURKA) is a major regulator of mitosis and an important driver of cancer progression." (PMID 29899121, 2018). "Drugs, which can induce c-Bax generation, such as inhibition of AURKA by MLN8237, probably have a better response in Bcl-2 driven cancers." (PMID 30013101, 2018). "Several other proteins such as AURKA, AURKB, CHEK1, BIRC5, CDC25B decreases their local PageRanks in cancer which means they become more controlled." (PMID 29370181, 2018). "All this implies that there is interplay between AURKA and the Wnt and Ras-MAPK signalling pathways and vice versa in different cancer settings." (PMID 29760449, 2018). "Another study indicated that AURKA suppresses CDDP‐induced apoptosis through phosphorylation of p73 and its sequestration in the cytoplasm in cancer cells." (PMID 28417568, 2017). "Thus vulnerability to AURKA inhibitors might not be limited to the loss of SMARCA4 in NSCLCs but might occur in other cancers with mutations in SMARCA4 or other SWI/SNF components that cause a loss of SWI/SNF function." (PMID 28102363, 2017). "Collectively, these observations raise a strong possibility that FAM83D coordinates cell cycle progression in human cancer cells by binding with HMMR, TPX2, and AURKA." (PMID 29088801, 2017). "For the first time, the functional interaction of AURKA and AURKB has been found, which aids in the protection of their stability, and partially explains their constant high expression and activity in cancers." (PMID 28595628, 2017). "The most attractive inhibitors are those that target cell cyclin dependent kinases (e.g. CDK1) and aurora kinases (e.g. AURKA, AURKB), which are abundantly expressed in various cancer types." (PMID 28183295, 2017). "Consistently, AURKA knockdown downregulated the expression of FOXM1 and that of the cancer stem cell markers c-Myc, SOX2 and Nanog in MDA-MB-231 cells." (PMID 28114286, 2017). "Aberrant expression and activation of aurora kinase A (AURKA) and eukaryotic translation initiation factor 4E (eIF4E) are detected in several cancer types." (PMID 28417568, 2017).
cancer (continued). "ZMYND8 gene is localized at chromosomal region 20q13, which also contains candidate breast cancer oncogenes: MYBL2 (MYB proto-oncogene like 2), ZNF217 (zinc finger protein 217), and AURKA (aurora kinase A)." (PMID 28055972, 2017). "The ectopic expression of AURKA and AURKB is closely correlated with carcinogenesis, the epithelial-to-mesenchymal transition, cancer cell stemness, and drug resistance." (PMID 28595628, 2017). "It has been shown that AURKA was involved in platinum-resistance and administration of either VX-680 or MLN8237 re-sensitized cancer cells to platinum and attenuated the migration ability of platinum-resistant NSCLC cells." (PMID 28147341, 2017). "Therefore, specific inhibition of Aurora kinase A may be useful as a cancer treatment." (PMID 27713168, 2016). "AURKA and CCNB1 are oncogenes overexpressed in many types of cancer and they are involved in progression of the cell cycle, and positively correlated with tumorigenesis, metastasis and chemotherapy resistance." (PMID 27355345, 2016). "Accordingly, a number of new AURKA inhibitors, such as ZM447439, Hesperadin, VX-680/MK-0457, AT9283 and AZD1152 are being developed to target malignant tumors and clinical trials are ongoing to investigate their efficacy." (PMID 27209210, 2016). "In this context, recent reports indicated that AURKA overexpression promotes activation of NF-κB and STAT3 pathways in these cancers." (PMID 25987188, 2015). "Consequently, the cell harboring a defective AURKA may lead to cancer." (PMID 25253995, 2014). "For example, the “Cancer, Cellular Movement, Cellular Growth and Proliferation” network encompasses EGFR, FGFR2 and other key genes, such as AURKA, a cell cycle checkpoint mediator, and SPP1, LAMA3 and GJA1, which play a role in cell communication." (PMID 23383013, 2013). "Dysregulation of AURKA and EGFR is observed in different types of cancer and is an important indicator of prognosis in cancer development." (PMID 23520446, 2013). "Considering the molecular subtypes, AURKA showed higher mRNA levels in ER-/HER2- and HER2+ tumors, whereas expression was lower in ER+/HER2- carcinomas." (PMID 23186136, 2012). "As well as identifying high frequency, differentially expressed genes, including known cancer genes such as PIK3CA and AURKA, we also used high amplitude regions to locate additional known (e.g. ERBB2 and CCNE1) and potential oncogenes." (PMID 20386695, 2010). "Since the AURKA gene is located, like the ZNF217 gene, at 20q13, a region frequently amplified in human cancers, our finding is of particular interest for several reasons." (PMID 21059223, 2010). "The SROs in these chromosome arms contains a number of protein coding genes, including well known critical cancer genes as BCL2 (18q22), DCC (18q21) and AURKA (20q13)." (PMID 20459617, 2010). "Moreover, based on the blue module genes screened by WGCNA and existing researches, AURKA, TPX2, CHEK1, and PLK1 were found to be highly related to NCAPH and were involved in the regulation of PI3K/AKT pathway in cancer." (PMID 38587786, 2025). "siRNA knockdown of RALA and AURKA inhibition by MLN8237 (VMLN) also did not affect pS194RALA detection in these cancers." (PMID 40568758, 2025). "For molecular validation, we selected AURKA as a control gene, expecting non-discriminatory effects between cancer and normal cells." (PMID 40180891, 2025). "In addition, AURKA expression was significantly and positively correlated with immune checkpoint targets such as CD274, LAG3, and CTLA4 in most cancer types." (PMID 40718709, 2025). "Among these genes, AURKA and STAG1 play important roles in cell division by regulating chromosome segregation and mitotic spindle formation and are considered promising targets for cancer therapy." (PMID 40815637, 2025).
cancer (continued). "The resulting compound (compound 19, containing an acrylamide moiety) exhibited the highest in vitro activity, selectively inhibiting both normal and cancer cells (LO2 IC50 = 23.39 μM; MDA-MB-231 IC50 = 1.54 μM), and showed strong inhibition of both AURKA and AURKB (AURKA IC50 = 1.7 nM)." (PMID 40949156, 2025). "Notably, AURKA expression showed a predominantly positive correlation with activated CD4+ T cells and T helper 2 cells across cancer types." (PMID 40718709, 2025). "Additionally, research also indicates that AURKA stimulates the EMT and the spread of tumours, specifically in cancers of the stomach and larynx, through the activation of the PI3K/AKT signalling cascade." (PMID 40702875, 2025). "The first described PPI inhibitor was Withanone, a natural compound that blocks intermolecular hydrophobic interactions between TPX2 and AurkA involved in the formation of the complex, hindering its functionality and impairing mitotic spindle organisation in MCF7 cancer cells." (PMID 39195284, 2024). "As both RAL-A and AURKA are overexpressed in cancer, regulation of mitochondrial fission could be one of the mechanisms by which RAL-A fuels cancer." (PMID 39334449, 2024). "Unlike normal cells, AURKA is localized beyond the nucleus in cancer cells, irrespective of cell cycle phase; where it can trigger a plethora of improper interactions, phosphorylation, and mislocalizations." (PMID 39334449, 2024). "PP6 depletion therefore leads to hyperactive TPX2-bound AurkA and may mimic the condition of AurkA/TPX2 complex overexpression in cancer." (PMID 39195284, 2024). "A positive correlation was found (r = 0.2) when we estimated how the correlation of AURKA protein expression with its SLR varied according to SLR change in different cancers, although this has no statistical significance (p = 0.714)." (PMID 39527514, 2024). "We next tested whether ectopic expression of AURKA blocks the induction of Hh signal-related genes and the re-expression of KRAS in cancer cells treated with a KRASG12C inhibitor." (PMID 38225225, 2024). "Because it has been suggested that overexpression of AURKA and AURKB is related to a more aggressive type of cancer such as TNBC, identifying molecules that could target the AURKs is a promising step toward developing novel therapies." (PMID 38886738, 2024). "These cancer hallmarks are regulated by various signalling pathways – including but not limited to phosphatidylinositol‐3‐kinase (PI3K)/AKT and catenin 1 (CTNNB1) pathways – in which AURKA plays a critical role, leading to malignant transformation." (PMID 38590119, 2024). "Compound 15 degrades AURKA with low DC50 value of 2.05 nM, which is 77-fold and 21-fold more selective toward AURKB and TTK and has an EC50 value of 39 nM against cancer MV4-11 cells." (PMID 39539259, 2024). "JG231 treatment did not disassociate the binding of AURKA and N-Myc, suggesting a potential bypass route present in the cancer cells." (PMID 39103353, 2024). "Aurora kinase A (AURKA) is a potent oncogene and an attractive target for cancer therapeutics." (PMID 38994036, 2024). "Upregulation of AURKA was observed in irradiated HCC cells, with concomitant overexpression of N‐cadherin and significantly elevated CD133 and CD44, characteristic features of EMT and cancer cell stemness (CSC), respectively." (PMID 38590119, 2024). "Since AURKA is overexpressed in various types of cancer, analysis of LIMK2 and AURKA levels could supplement standard staging information in primary biopsy samples." (PMID 39334449, 2024). "Other groups have used alternative software tools to measure genome-wide APA changes in TCGA samples, but in these studies AURKA SLR changes were not reported in the published lists of genes with cancer-dependent changes in SLR." (PMID 39527514, 2024). "For instance, AURKA promoted EMT and cancer stem cell behaviors via the PI3K/AKT pathway in HCC." (PMID 36973424, 2023).